PPARG (peroxisome proliferator activated receptor gamma)
Diseases named in the same sentence as PPARG in open-access papers (continued):
Sharing a sentence is not in itself a finding about the gene and the disease.
colorectal cancer (continued). "Therefore, pharmacological activation of PPARγ and/or induction of SSAT may represent a therapeutic or preventive strategy for treating colorectal cancer." (PMID 16854216, 2006). "In addition, butyrate targets peroxisome proliferator-activated receptor gamma (PPARγ) a type II nuclear receptor that activates caspase-3, increases caspase-8 and -9 activity and reduces expression of XIAP and survivin leading to apoptosis in colorectal cancer cells (Caco-2 cells)." (PMID 31067776, 2019). "Epigenetic silencing of PPARG in colorectal cancer may be a significant prognostic marker of tumor progression, and methylation on a specific region of the promoter is strongly correlated with PPARγ lack of expression in primary colorectal cancers and with patients' poor prognosis." (PMID 23028383, 2012).
lipodystrophy (122 papers, 2007 to 2025). "PPARG missense variants with a lipodystrophy-causing MITER score (≤-2) showed a similar magnitude collective association with lower adult body fat percentage than our other prediction based missense variant masks (p = 9.70 × 10−5)." (PMID 39809772, 2025). "Prior studies have shown that ASXL2 regulates lipid homeostasis; notably, ASXL2‐deficient mice develop lipodystrophy due to reduced PPARγ activity." (PMID 40300851, 2025). "We identified one heterozygous stop-gain variant in the PPARγ gene among the filtered results for the genes associated with familial partial lipodystrophies." (PMID 39596129, 2024). "Previous studies reported that a reduction in PPARγ protein’s transcriptional activity of ≥ 30% is sufficient to cause partial lipodystrophy." (PMID 39596129, 2024). "Heterozygous knock-in mouse models carrying the dominant negative PPARγ mutations L466A and P465L, which were found in humans with lipodystrophy and/or the metabolic syndrome, recapitulated some of the features of the human phenotypes." (PMID 38727299, 2024). "Genetic lipodystrophies due to loss-of-function PPARG variants occur at a low frequency estimated at 1:100,000 individuals." (PMID 39398333, 2024). "Thiazolidinediones are associated with improved HbA1c and triglycerides in all lipodystrophy (n = 13), improved HbA1c in PPARG (n = 5), and improved triglycerides in LMNA (n = 7)." (PMID 37794082, 2023). "The weighted loci in this cluster (N = 37 loci) are lipodystrophy and adiposity-related variants (PPARG, IRS1, LYPLAL1, and DNAH10)." (PMID 37790568, 2023). "It was also suggested that adipose tissue-specific ablation of PPARγ causes progressive lipodystrophy." (PMID 37106328, 2023). "TZDs have attracted specific interest in familial partial lipodystrophy type 3 (FPLD3), the second commonest monogenic lipodystrophy, which is caused by mutations in the PPARG gene itself." (PMID 35618782, 2022). "Mutations in genes associated with lipodystrophy, such as the peroxisome proliferator-activated receptor-gamma (PPARγ), lamin A/C (LMNA), and hormone-sensitive lipase genes, are potential therapeutic targets for NAFLD." (PMID 36304168, 2022). "Taken together, we identified two previously uncharacterized lipodystrophy mutations that are predicted to interfere with two interaction interfaces of PPARγ that remain functionally poorly understood." (PMID 36402763, 2022). "Peroxisome proliferator-activated receptor γ (PPARγ) is the master regulator of adipocyte differentiation, and mutations that interfere with its function cause lipodystrophy." (PMID 36402763, 2022). "We observed that PPARγ is a gene involved in lipodystrophy development and is closely associated with the regulation of the other genes altered in this pathology." (PMID 36432429, 2022). "In vivo studies have revealed the importance of PPARγ for adipocytes production and survival in animals as negative mutations (heterozygous and dominant) in the PPARγ in humans cause lipodystrophy." (PMID 34830341, 2021). "Features of PCOS were similarly observed in 3 patients with partial lipodystrophy, including 1 patient with digenic IR (P2) and 1 patient with heterozygous pathogenic variants in PPARG (P8)." (PMID 33901270, 2021). "Inactivating germline mutations of PPARG in humans causes severe lipodystrophy, severe hypertension, diabetes, dyslipidemia, and hepatic steatosis." (PMID 34445339, 2021). "To confirm the association of lipodystrophy and hepatic metastasis, we administered Bo1 cancer cells to mice conditionally deleted of PPARγ, which is essential for adipocyte differentiation in all fat depots, using adiponectin-Cre (PPAR ADQ)." (PMID 32879136, 2020). "For example, severe mutations in PPARG cause monogenic lipodystrophy, whereas less severe variants are associated with complex polygenic forms of lipodystrophy." (PMID 31034465, 2019).
lipodystrophy (continued). "Despite these limitations, this study highlighted important insights into a challenging disease for which early recognition is based on clinical criteria and broadened our knowledge of PPARγ mutations in lipodystrophy." (PMID 30622652, 2019). "Both caveolin-1 and PPARγ are among the group of proteins in which mutation results in lipodystrophy." (PMID 28420992, 2017). "Consistently, mutations of the PPARγ gene have been implicated in lipodystrophy as well as other metabolic diseases such as hypertension and insulin resistance in humans." (PMID 24904744, 2014). "Humans harboring loss of function PPARγ mutation (P467L) show a pattern of lipodystrophy and are insulin resistant." (PMID 22168210, 2011). "As such, it is not surprisingthat a number of recent studies have indicated that certain drugs known to be associatedwith lipodystrophy dysregulate PPARγ." (PMID 19325916, 2009). "Alterations in PPARγ expression have been implicated as a factor in the mechanism of HIV-1-associated lipodystrophy." (PMID 19325916, 2009). "PPARγ deficiency due to either haploinsufficiency or to dominant negative activity elicits familial partial lipodystrophy (Dunnigan) type 3 whereas reduced PPARγ expression has been observed in fat from patients with HAART-associated lipodystrophy." (PMID 18752661, 2008). "Medical histories reveal that in addition to lipodystrophy andhypertension (both frequently associated with PPARG mutations), the femalecarrier also experienced oligomenorrhea and hirsutism, and required ARTintervention to conceive." (PMID 18309368, 2008). "This may suggest the potential role of lipodystrophy-related PPARγ variants in inducing early metabolic complications." (PMID 39479521, 2024). "Biallelic PPARG variants (compound heterozygous) were related to a congenital generalized lipodystrophy phenotype, emphasizing the genetic heterogeneity of congenital lipodystrophies." (PMID 39398333, 2024). "Thus, it is critical to identify the underlying mechanisms by which PPARγ alters adipose tissue homeostasis in partial lipodystrophy." (PMID 36835312, 2023). "We were specifically interested in any evidence of a greater or lesser response in partial lipodystrophy caused by PPARG variants than in other lipodystrophy subtypes, as TZDs are potent ligands for the product of the PPARG gene, the master regulator of adipocyte differentiation." (PMID 37794082, 2023). "Mutations in PPARγ lead to lipodystrophy, but the mechanisms by which the mutations affect the activity in chromatin is unknown." (PMID 36402763, 2022). "Patients with PPARG-DM caused by AF1 variants often lack typical lipodystrophy features." (PMID 34764936, 2021). "Our and others early studies showed that under MetS or EMS condition, the expression of C/EBPα and PPARγ are drastically reduced, which causes lipodystrophy and adipose tissue inflammation as well as promotes the accumulation of ROS and NO—two inducers of defective adipogenic differentiation." (PMID 34732209, 2021). "Mutations in Lmna and Pparγ are well recognized in familial partial lipodystrophies and therefore could play a role in this acquired form of lipodystrophy." (PMID 34383714, 2021). "Additionally, since PPARγ dysregulation is closely associated with the development of metabolic diseases, such as impaired glucose tolerance and lipodystrophy, careful consideration should be taken before applying these findings clinically." (PMID 32354153, 2020). "However, there are also other reports suggesting that PPARγ bearing mutations in DBD or LBD are associated with lipodystrophy." (PMID 32973516, 2020). "Moreover, dominant-negative PPARγ mutation in humans and PPARγ deficiency in mice lead to lipodystrophy, and PPARγ-deficient embryonic stem cells are unable to differentiate into adipocytes." (PMID 30742088, 2019). "PPARγ mutations represent one genetic type of lipodystrophy." (PMID 30396151, 2018).
lipodystrophy (continued). "For instance, aP2- and adiponectin-driven loss of PPARγ in adipose tissues consistently lead to impaired adipocyte differentiation and reduced fat weights or lipodystrophy, though different animal models show improved or worsen insulin sensitivity depend on the extent of PPARγ deficiency." (PMID 30186237, 2018). "Interestingly, both caveolin-1 and PPARγ are among the group of proteins in which mutations result in lipodystrophy." (PMID 28420992, 2017). "Mutations in PPARγ (PPARG) or lamin A/C (LMNA) can cause partial lipodystrophy." (PMID 27225296, 2016). "Dominant negative PPARγ mutations in humans also result in lipodystrophy." (PMID 23049863, 2012). "Thus, it remains unclear whether people with IR due to PPARG variants are more or indeed less sensitive to TZDs than people with other forms of lipodystrophy." (PMID 37794082, 2023). "The nuclear hormone receptor peroxisome proliferator-activated receptor-γ (PPARγ), encoded by PPARG, is the master regulator of adipose tissue biogenesis, and its pharmacological activation by pioglitazone or other thiazolidinediones (TZDs) seems an obvious strategy in lipodystrophy." (PMID 35618782, 2022). "Mendelian genetic studies have identified rare variants in genes such as PPARG, a master regulator of adipocyte differentiation, and INSR, the insulin receptor, associated with lipodystrophies and extreme forms of central body fat distribution." (PMID 40912257, 2025). "Both “Lipodystrophy 1” and “Lipodystrophy 2“ included PPARG among the top-weighted genes, which is known for its role in adipose tissue differentiation and as target of the insulin sensitizing thiazolidinediones." (PMID 39278900, 2024). "For example, the Lipodystrophy 1 and 2 clusters included rs17036160 near PPARG, the target of thiazolidinediones, which promote insulin sensitivity." (PMID 37886436, 2023). "An extreme example of this paradigm occurs in Mendelian lipodystrophies, such as those caused by missense mutations in the LMNA and PPARG genes." (PMID 35773277, 2022). "In summary, the PPARγ lipodystrophy-associated mutations R212Q and E379K, located in the hinge and LBD, respectively, both markedly destabilize the binding of the PPARγ:RXR heterodimer to natural imperfect PPREs but through effects on different interfaces." (PMID 36402763, 2022). "However, in the case of acquired lipodystrophy, the origin remains unclear, despite the expression of specific genes, such as peroxisome proliferator-activated receptor gamma (PPARγ), being implicated in lipodystrophy associated with antiretroviral therapy (ART)." (PMID 36432429, 2022). "Our data demonstrate how in-depth analyses of lipodystrophy mutants can unravel molecular mechanisms of PPARγ function." (PMID 36402763, 2022). "Bone formation also increased in mice with severe lipodystrophy induced by a knock-out of peroxisome proliferator-activated receptor gamma (PPARγ) in white fat and the inverse correlation between bone density and MAT was also observed in leptin-deficient mice." (PMID 34574647, 2021). "Marrow Adipose Tissue in lipodystrophy has not been sufficiently quantified due to the rarity of this disorder; though it has been investigated in rodents in other less severe forms of lipodystrophy (PPARγ +/- or Cav1-/-)." (PMID 35145475, 2021). "This approach was needed to reveal the lipodystrophic phenotype of previous mouse models of partial lipodystrophy, such as the P467L PPARγ knockin mouse model and the Cidec null model." (PMID 33691105, 2021). "Consistent with the observation from rosiglitazone-treated adipose-specific Seipin knockout mice and troglitazone-treated lipodystrophy patients, sWAT in our study showed a significant response to a PPARγ agonist." (PMID 32797353, 2021). "Abnormal expression of PPARγ in humans and insufficiency of PPARγ in mice can result in lipodystrophy, indicating sufficient PPARγ expression is indispensable to the maintenance of adipogenesis." (PMID 33425901, 2020).
lipodystrophy (continued). "Variants of type FPLD3, a rather stereotypical form of lipodystrophy of type PPARγ ligand resistance syndrome (PLRS), are due to heterozygous mutations in the peroxisome proliferator-activated receptor γ (PPARγ) gene." (PMID 33233602, 2020). "Examination of the raw images of CEBPA/AGPAT2 ablated cells revealed cells with decreased lipid accumulation compared to controls, but did not appear distinctive on manual visual inspection in comparison to ablation of other lipodystrophy genes such as PPARG." (PMID 30940487, 2019). "Examination of the raw images of BSCL2/PLIN1 ablated cells revealed cells with decreased lipid accumulation overall, but with strikingly large residual lipid droplets as compared to control cells or cells ablated for other lipodystrophy genes such as PPARG." (PMID 30940487, 2019). "In previous reports, specific PPARγ deletion in adipose tissues in young adult animals results in lipodystrophy or massive adipocyte death, indicting an indispensable role of PPARγ in adipose tissue development and survival." (PMID 30186237, 2018). "The common duplication of PMP22 was ruled out by clinical-grade testing, and genes known to cause lipodystrophy (LMNA, PPARG, EMD, AGPAT2, BSCL2) were also sequenced." (PMID 28050599, 2017). "Mice with adipose-specific deletion of PPARγ exhibit lipodystrophy and dramatically decreased serum adiponectin and resistin levels when compared with wild type mice." (PMID 28515350, 2017). "Mutations in several genes have been found in patients with inherited lipodystrophies, including mutations in LMNA, PPARG, AKT2 and ZMPSTE24 in partial lipodystrophy, and mutations in AGPAT2, BSCL2, CAV1 and PTRF in congenital total lipodystrophy." (PMID 26987365, 2016). "Consistently, PPARγ knockout mice lack terminally differentiated adipose tissues and develop fatty liver and lipodystrophy." (PMID 24904744, 2014). "HIV-infected patients with lipodystrophy had been found to have a lower PPARγ level in the subcutaneous adipose tissue, and a higher waist-to-hip ratio, higher serum insulin and triglyceride levels." (PMID 23145084, 2012). "Several studiesevaluated the expression of PGC1α and PPARγ in adipose tissue from long-term ART treatedHIV-infected patients with lipodystrophy." (PMID 19125203, 2009). "PPARG-related lipodystrophy is higher among females after puberty, which may have early menarche and polycystic ovary syndrome." (PMID 38951919, 2024). "PPARγ is another adipogenesis marker that plays a pivotal role in adipocyte differentiation, and its deficiency is associated with impaired BAT thermogenesis, lipodystrophy, and a worsened metabolic phenotype." (PMID 38987854, 2024). "Using real-time quantitative PCR, we further showed that AT alleviated lipodystrophy-induced activation of hepatic lipogenesis (Pparγ, Fas, and Scd1) and inhibition of triglyceride-rich lipoprotein packaging (Mtp) and fatty acid β-oxidation (Pparα and Cpt1α) in Seipin/Apoe dKO mice." (PMID 38525541, 2024). "Although we found small scale evidence supporting greater A1c reduction with TZDs in PPARG vs. LMNA-related lipodystrophy, only 5 patients with PPARG-related lipodystrophy in whom TZD effects were clearly described were reported, and responses were inconsistent." (PMID 37794082, 2023). "In vivo studies have demonstrated that the absence of PPARγ in adipose tissues can hamper adipocyte differentiation and cause lipodystrophy." (PMID 37235264, 2023). "Mice deficient in PPARγ have no adipose tissue, and PPARγ mutations in humans are associated with severe lipodystrophy." (PMID 37909330, 2023). "However, in mice with partial lipodystrophy, both residual perigonadal and preserved inguinal fat depots respond to PPARγ activation, leading to a compensatory increase in the workload due to inguinal fat." (PMID 36835312, 2023).